ENSG00000280537 (novel protein, SLC23A3-NHEJ1 readthrough)
Gene: Protein-coding gene on chromosome 2 (219,075,329 to 219,170,827, reverse strand). Ensembl gene ENSG00000280537.
Genetic constraint (gnomAD): Missense variants: 125 observed, 123.48 expected, observed/expected ratio (o/e) 1.01, 90% interval 0.88 to 1.17. Synonymous variants: 50 observed, 53.7 expected, observed/expected ratio (o/e) 0.93, 90% interval 0.74 to 1.18.